TMEM79 (transmembrane protein 79)
Description:
Contributes to the epidermal integrity and skin barrier function. Plays a role in the lamellar granule (LG) secretory system and in the stratum corneum (SC) epithelial cell formation (By similarity).
Synonyms: MATT; MGC13102; FLJ16057; FLJ32254
Tractability: Antibody: UniProt predicts a signal peptide or a membrane-spanning region. PROTAC: ubiquitination databases record sites on it.
Gene: Protein-coding gene on chromosome 1 (156,282,935 to 156,293,185, forward strand). Ensembl gene ENSG00000163472.
Subcellular location: Lysosome; Golgi apparatus, trans- Golgi network; Membrane
Subcellular location (Human Protein Atlas): Nucleoli fibrillar center
Gene Ontology:
Molecular function: identical protein binding; protein binding
Biological process: epithelial cell maturation; establishment of skin barrier; positive regulation of epidermis development; regulated exocytosis
Cellular component: lysosomal membrane; trans-Golgi network membrane; cytoplasm; Golgi apparatus; lysosome; membrane
Genetic constraint (gnomAD): Loss-of-function variants: 30 observed, 31.25 expected, observed/expected ratio (o/e) 0.96, 90% interval 0.72 to 1.3. The upper end of that interval is the gene's LOEUF score, 1.3, which puts it in group 5 of 6, group 1 being the genes least tolerant of losing a copy. Missense variants: 509 observed, 533.89 expected, observed/expected ratio (o/e) 0.95, 90% interval 0.89 to 1.03. Synonymous variants: 213 observed, 232.16 expected, observed/expected ratio (o/e) 0.92, 90% interval 0.82 to 1.03.
Homologues: Orthologues: chimpanzee TMEM79 (99% identical), macaque TMEM79 (98% identical), pig TMEM79 (87% identical), guinea pig TMEM79 (86% identical), dog TMEM79 (85% identical), mouse Tmem79 (83% identical), rat Tmem79 (82% identical), tropical clawed frog tmem79 (34% identical), zebrafish tmem79b (30% identical), zebrafish tmem79a (26% identical).
Diseases named in the same sentence as TMEM79 in open-access papers:
TMEM79 is named in the same sentence as 28 diseases in open-access papers, as found by Europe PMC text mining. Sharing a sentence is not in itself a finding about the gene and the disease. The quoted sentences say what the papers report.
prostate carcinoma (4 papers, 2013 to 2025). A carcinoma that arises from epithelial cells of the prostate gland. "High expression of TMEM79 plays a role in promoting many cancer types, and it has been studied that TMEM79 is a diagnostic marker for prostate cancer." (PMID 37936239, 2023). "TMEM79 has been reported to be associated with immune cell infiltration in prostate cancer." (PMID 37936239, 2023). "TMEM79 has been found to be a possible diagnostic marker for prostate cancer." (PMID 37936239, 2023). "The underlying mechanisms and potential role of loss of TMEM79 expression in prostate cancer cells are unknown as the function of TMEM79 has yet to be elucidated." (PMID 26237329, 2015). "Recently, researchers identified previously uncharacterized genes, transmembrane protein 79 (TMEM79), and ACOXL1, as potential diagnostic markers for prostate cancer using patient-derived prostate-specific proteome." (PMID 41065381, 2025). "On the other hand, the levels of TMEM79 were reduced in three types of cancer, consisting of head and neck squamous cell carcinoma, renal suspicious cell carcinoma, and prostate cancer." (PMID 37936239, 2023). "Both Pearson and Spearman correlations also showed that there is a moderate inverse relationship between the membranous expression of TMEM79 and prostate cancer." (PMID 26237329, 2015). "Our data provides a starting point for further functional studies to explore the molecular repertoire of normal and diseased prostate including potential prostate cancer markers such as TMEM79 and ACOXL." (PMID 26237329, 2015). "Thus, TMEM79 displayed a high sensitivity (81%) and specificity (84%) to distinguish benign prostate glands from prostate cancer." (PMID 26237329, 2015). "However, future functional studies of TMEM79 and further sequencing of prostate tumor tissue will be important to increase our knowledge regarding this promising prostate cancer marker." (PMID 26237329, 2015). "Using this strategy TMEM79 and ACOXL were identified as two novel candidate biomarkers for prostate cancer." (PMID 26237329, 2015). "Approximately 81% (127/156) of benign prostate tissue samples showed a positive membranous expression of TMEM79 and approximately 84% (148/156) of prostate cancer tissue samples did not express TMEM79." (PMID 26237329, 2015). "TMEM79 and SMG5 complexes may be prognostic markers for prostate cancer." (PMID 37936239, 2023). "However, further analysis of TMEM79 and ACOXL at a number of levels including functional analysis, analysis of ACOXL expression levels in matched tissue and serum are warranted in prostate cancer tissue in order to determine if they have clinical impact in disease screening." (PMID 26237329, 2015). "For ETS fusion-negative prostate cancers subtypes, novel gene fusions have also been identified, including SLC45A3:BRAF, ESRP1:RAF1, SLC45A3:BRAF, ESRP1:RAF1, C15orf21:Myc, EPB41:BRAF, and TMEM79:SMG5." (PMID 23957008, 2013).
skin inflammation (4 papers, 2016 to 2025). "Additionally, two groups demonstrated that homozygous mutation of TMEM79 is responsible for the spontaneous dermatitis phenotype in flaky tail mice which was originally thought caused solely by FLG mutations." (PMID 27777593, 2016). "Both Tmem79Ma/Ma mutant mice and Tmem79 −/− KO mice exhibit dermatitis-like skin inflammation, a defective skin barrier, and a desorganized SC." (PMID 40698039, 2025). "Mouse studies suggest that a nonsense mutation Y208Stop in transmembrane protein 79 (TMEM79), identified in the “flaky tail” mice, results in spontaneous skin inflammation that is exaggerated in the BALB/c background." (PMID 35052551, 2021). "Transmembrane protein 79 (TMEM79, a predisposition gene for AD) can specifically inhibit ubiquitin-specific peptidase 8 deubiquitination, and its deficiency shows more susceptible to developing skin inflammation, compromised barrier function, and spontaneous dermatitis." (PMID 35874824, 2022).
atopic dermatitis (2 papers, 2020 to 2025). "TMEM79 is a predisposition gene for Atopic dermatitis, suggesting deregulation of Wnt/FZD signaling a possible cause for this most common yet enigmatic inflammatory skin disease." (PMID 32924931, 2020). "Of interests, a Tmem79 gene mutation in matted (Tmem79ma/ma) mice causes atopic dermatitis (AD) and matted hair phenotypes, and TMEM79 is a predisposition gene for AD in human." (PMID 32924931, 2020). "Interestingly, TMEM79 is a predisposition gene for atopic dermatitis (AD), the most common chronic and relapsing inflammatory skin disease that affects 20% children and 5–10% adults but with poorly defined molecular etiology." (PMID 32924931, 2020). "The TMEM79 gene, also known as Mattrin, was originally identified in the Flaky tail (ft/ft) mouse line a well-established model for atopic dermatitis." (PMID 40698039, 2025).
heart failure (2 papers, 2011 to 2022). Inability of the heart to pump blood at an adequate rate to meet tissue metabolic requirements. "UBN1, NGF and FECH genes displayed similar statistically significant regulation (up or down regulated) in hearts samples from heart failure patients but expression of the three remaining genes (TMEM79, FBXW7 and SLC43A2) could not be quantified, probably because of their low expression in heart." (PMID 21731613, 2011). "Analysis of the leucocyte transcriptome in 294 patients without overt heart failure revealed that levels of FECH, TMEM79, FBXW7, NGFB, ALK, UBN1, and SLC43A2 in peripheral blood were able to predict ALVD with 87% accuracy and 100% precision." (PMID 35722087, 2022).
allergic reactions (1 paper, 2025). "TMEM79 (transmembrane protein 79) is a transmembrane protein associated with skin barrier function, particularly in skin protection, allergic reactions, and eczema." (PMID 39796272, 2025).
liver cancer (1 paper, 2023). An epithelial or non-epithelial malignant neoplasm that arises from the liver. "Correlation analysis showed that TMEM79 and SMG5 played a role in promoting liver cancer progression (p = 0.001, R = 0.202)." (PMID 37936239, 2023). "The expression levels of TMEM79-related derivatives in 374 liver cancer patients and 50 normal human liver tissues were examined on the TCGA data sets." (PMID 37936239, 2023). "We found that TMEM79 was differentially expressed in liver cancer tissues and normal tissues." (PMID 37936239, 2023).
malignant melanoma (1 paper, 2023). "TMEM79 is a potential novel biomarker for BPH, and may act as a pivotal factor involved in immune response and tumor cell development in malignant melanoma tumorigenesis." (PMID 37936239, 2023).
skin itching (1 paper, 2025). "Mutations in the TMEM79 gene (also known as the MATT gene) can cause a decrease in the level of the protein mattrin it encodes, hinder the secretion of the contents of the lamellar bodies, and damage the transmission of the components of the lamellar bodies, causing skin itching and skin lesions." (PMID 41031084, 2025).
tumor (7 papers, 2015 to 2026). "This article focuses on not only the prognostic role of TMEM79 and its biological significance, including immuno-infiltration, tumor mutations and drug sensitivity, but also the interaction with SMG5 in HCC." (PMID 37936239, 2023). "The molecules that were differentially expressed in tumor and normal tissues by R software analysis were TMEM79, SMG5, NAA35, SLC45A3, FLG, TMEM254." (PMID 37936239, 2023). "There was a significant correlation between the expression of TMEM79 and tumor-infiltrating immune cells, and a positive correlation between macrophages and dendritic cells." (PMID 37936239, 2023). "The findings indicated that in tumor tissue when compared to normal tissue, six factors, among them TMEM79, were expressed differently." (PMID 37936239, 2023). "A novel in-frame gene fusion (TMEM79::NTRK1) was identified in a single tumor sample (0.5%)." (PMID 41977128, 2026). "TMEM79 showed a noteworthy correlation with the immune cells that infiltrated the tumor." (PMID 37936239, 2023). "Notably, TMEM79 may serve as a potential tumor immune marker for immunotherapy in HCC." (PMID 37936239, 2023). "Patients with high TMEM79 and SMG5 expression had higher tumor stage and were more likely to metastasize to distant sites." (PMID 37936239, 2023).
cancer (4 papers, 2021 to 2025). A tumor composed of atypical neoplastic, often pleomorphic cells that invade other tissues. "TMEM79 has been reported to play diagnostic and prognostic markers in a variety of cancers and was found to be closely associated with immune infiltration." (PMID 37936239, 2023). "Previous studies have shown that EGR1, TMEM79, and CRACR2A are closely related to the progression of a variety of cancers, and it is worthwhile to further explore their molecular mechanisms." (PMID 34853602, 2021).
TMEM79 also shares sentences with these, for which no sentence is quoted: dermatitis (2 papers); bile duct cancer (1); breast carcinoma (1); colon cancer (1); eczema (1); endometrial cancer (1); esophageal cancer (1); gastric cancer (1); head and neck squamous cell carcinoma (1); hepatocellular carcinoma (1); inflammatory skin disease (1); lung adenocarcinoma (1); rectal adenocarcinoma (1); renal clear cell carcinoma (1); renal papillary cell carcinoma (1); spina bifida (1); thyroid cancer (1); tumor of the prostate (1).